DERPC (DERPC proline and glycine rich nuclear protein)
Description:
Potential tumor suppressor. Inhibits prostate tumor cell growth, when overexpressed.
Tractability: No criterion of Open Targets' tractability assessment is met for any kind of drug.
Gene: Protein-coding gene on chromosome 16 (69,118,010 to 69,132,588, reverse strand). Ensembl gene ENSG00000286140.
Subcellular location: Nucleus
Subcellular location (Human Protein Atlas): Nucleoplasm
Gene Ontology:
Cellular component: extracellular exosome; nucleoplasm; nucleus
Genetic constraint (gnomAD): Loss-of-function variants: 0 observed, 0.48 expected, observed/expected ratio (o/e) 0, 90% interval 0 to 1.84. That is too few expected variants to judge how well the gene tolerates losing a copy. Missense variants: 19 observed, 16.53 expected, observed/expected ratio (o/e) 1.15, 90% interval 0.8 to 1.67. Synonymous variants: 4 observed, 5.26 expected, observed/expected ratio (o/e) 0.76, 90% interval 0.37 to 1.64.
Homologues: Orthologues: macaque DERPC (98% identical), dog DERPC (91% identical), pig DERPC (90% identical), guinea pig DERPC (89% identical), mouse Derpc (87% identical), rat Chtf8 (86% identical), chimpanzee DERPC (81% identical).